ZMYND8 (zinc finger MYND-type containing 8)
Diseases named in the same sentence as ZMYND8 in open-access papers (continued):
Sharing a sentence is not in itself a finding about the gene and the disease.
tumor (continued). "It has been demonstrated that (ZMYND8 suppresses stemness, drug resistance, and tumor-promoting genes, which are hallmarks of cancer." (PMID 36520265, 2022). "Analysis of various tumor cell lines in the CCLE database showed that the expression level of ZMYND8 in NB cells was significantly higher." (PMID 36438198, 2022). "In this review, we summarize the evidence for both pro-oncogenic and tumor-suppressive effects of ZMYND8 in various types of cancer." (PMID 33670804, 2021). "Analysis of the Clinical Proteomic Tumor Analysis Consortium (CPTAC) ccRCC dataset revealed that both ZMYND8 mRNA and protein expression are significantly elevated in primary ccRCC compared with adjacent normal kidney tissues." (PMID 33593912, 2021). "ZMYND8 typically functions as a tumor suppressor, and binding to the H3K4me1-H4K14ac modifications has been found to inhibit the expression of genes associated with cancer metastasis." (PMID 34298819, 2021). "The titles and abstracts of the identified articles concerning ZMYND8, RACK7, cancer, angiogenesis, proliferation, invasiveness, metastasis, and tumor growth were included." (PMID 33670804, 2021). "We conducted a PubMed literature search, using a combination of the following keywords and their variants: ZMYND8, RACK7, cancers, neoplasms, oncogenesis, carcinogenesis, and epigenetic regulation (up to November 30, 2020)." (PMID 33670804, 2021). "Overexpressing ZMYND8 transcriptionally represses the expression of drug resistance, stemness, and tumor-promoting genes by repressing their poised promoters in association with KDM5C and EZH2." (PMID 33323928, 2020). "We demonstrate that zinc-finger MYND type-8 (ZMYND8), a putative chromatin reader, suppresses stemness, drug resistance, and tumor-promoting genes, which are hallmarks of cancer." (PMID 33323928, 2020). "ZMYND8 has been previously reported to be a potent tumor suppressor by inhibiting proliferation and metastasis." (PMID 33323928, 2020). "Cumulatively, in vitro and in vivo results prove that tumor suppressor ZMYND8 chemo-sensitizes via transcriptional repression of drug resistance, migration, and stemness genes." (PMID 33323928, 2020). "Expression levels of PYGO2, KDM5B, PHF20L1, and ZMYND8 were also significantly higher in tumor samples compared to that in non-tumor breast tissue." (PMID 28055972, 2017). "Additionally, Ki67 staining indicated that the combination of CFZ and ZMYND8‐OE significantly attenuated the proliferative capacity of MM tumor cells." (PMID 40347515, 2025). "Furthermore, ZMYND8 upregulation augments the secretion of CSF1, a pivotal chemokine instrumental in recruiting and polarizing tumor-associated macrophages (TAMs) toward an M2-like, immunosuppressive phenotype that supports metastatic progression." (PMID 41297414, 2025). "NAC water feeding significantly restored the ZMYND8-KO tumor incidence in mice." (PMID 38488001, 2024). "ZMYND8 KO equally reduced the frequency of 4T1 tumor initiation in NSG and BALB/c mice." (PMID 38488001, 2024). "ZMYND8 was previously recognized as a tumor suppressor in several types of tumors." (PMID 36674511, 2023). "We observed increased 5hmC levels in H3K4me3 regions in genes relating to cell proliferation, such as CDK6 and ZMYND8, and reduced 5hmC levels in H3K4me3 regions in genes that may be related to tumor suppression, such as ARHGAP26 and GLI3." (PMID 37372359, 2023). "It has been known that ZMYND8 also exerts tumor suppression." (PMID 36520265, 2022). "ZMYND8 Promotes Tumor Migration and Invasion via Interacting with EZH2 in ccRCC Cells." (PMID 33593912, 2021). "The controversy about KDM5C and ZMYND8's function in tumorigenesis might be due to the different role they play in different stages of tumor." (PMID 33977073, 2021). "In addition, ZMYND8 knockdown downregulates the stemness-related genes, prevents tumor cell differentiation, and maintains cancer cells in an undifferentiated state." (PMID 33670804, 2021).
tumor (continued). "In addition to the suppression of cell proliferation, ZMYND8 also affects the tumor cell migration and invasion." (PMID 33670804, 2021). "The interaction between ZMYND8 and various binding partners is considered to be crucial in determining whether the function of ZMYND8 is pro-oncogenic or tumor suppressive." (PMID 33670804, 2021). "For example, the interaction between ZMYND8 and PKCβ or TROJAN may induce pro-oncogenic effects, while interaction between ZMYND8 and KDM5C, KDM5D, or ZNF592 may cause tumor-suppressive effects." (PMID 33670804, 2021). "Therefore, our results indicate that ZMYND8 in association with the corepressor complex (KDM5C and EZH2) transcriptionally represses the poised tumor-promoting genes by removing H3K4Me3 and reinstating H3K27Me3 levels." (PMID 33323928, 2020). "Since we observed that a lower dose of chemotherapy led to gain in chemo-resistance, migration, and stemness, we hypothesized that ectopic expression of ZMYND8 could lead to the reversal of tumor-promoting phenotypes." (PMID 33323928, 2020). "This led us to hypothesize that ZMYND8 overexpression represses the tumor-promoting target gene expression through the alteration of poised epigenetic states of their promoters." (PMID 33323928, 2020). "Therefore, we wanted to investigate the anti-cancer role of ZMYND8 in the context of drug resistance and the stemness properties of tumor cells." (PMID 33323928, 2020). "We next evaluated whether gene-transcription changes initiated by ZMYND8 overexpression in doxorubicin-treated cells are also reflected in tumor regression phenotypes." (PMID 33323928, 2020). "Thus, our results indicate the potential role of ZMYND8 in suppressing gain in stemness and drug resistance properties of tumor cells, a phenomenon that is molecularly governed by EMT." (PMID 33323928, 2020). "Therefore, our results showed that ZMYND8 regulates the poised epigenetic state of these tumor-promoting genes by modulating their respective epigenetic regulators, KDM5C and EZH2." (PMID 33323928, 2020). "However, 4T1 tumor regression by ZMYND8 KO was much greater in BALB/c mice than NSG mice." (PMID 38488001, 2024). "Therefore, ZMYND8 is important for tumor cell proliferation, angiogenesis, and tumor growth." (PMID 33670804, 2021). "IHC analysis of tumor tissues revealed that the protein levels of ZMYND8 and CEBPE in the ZMYND8‐KD group were significantly lower than those in the control group and that the Ki67 levels increased after ZMYND8 knockdown." (PMID 40347515, 2025). "Our initial assessment revealed that ZMYND8 is significantly upregulated in human TNBC-SM lesions, and its high expression correlates with an immunosuppressive tumor microenvironment, characterized by M2 macrophage infiltration, and poor patient survival." (PMID 41297414, 2025). "Here, we showed that ZMYND8 reduced ROS and iron to inhibit ferroptosis in aldehyde dehydrogenase–high (ALDHhi) BCSCs, leading to BCSC expansion and tumor initiation in mice." (PMID 38488001, 2024). "NRF2 phenocopied ZMYND8 to enhance BCSC stemness and tumor initiation by inhibiting ROS and ferroptosis." (PMID 38488001, 2024). "ZMYND8 and NRF2 are induced in ALDHhi BCSCs and cooperate to inhibit BCSC ferroptosis leading to tumor initiation in mice." (PMID 38488001, 2024). "The proteins RACK7/ZMYND8 and BS69/ZMYND11 are cancer related; they are tumor suppressive or oncogenic with context dependency upon histologic origin." (PMID 36520265, 2022). "ZMYND8 and the KDM5 family cooperatively act on super-enhancer regions and are crucial regulators of expression and repression of oncogenes and tumor-suppressor genes in various types of cancer." (PMID 33670804, 2021). "ZMYND8 knockout also decreases the microvessel density in the mammary fat pad MDA-MB-231 tumor and subcutaneous MAF-7 tumor in SCID mice, which further supports the induction of angiogenesis by ZMYND8." (PMID 33670804, 2021).
tumor (continued). "ZMYND8 (zinc finger, MYND domain-containing protein) is a putative chromatin reader, with tumor-suppressive functions." (PMID 33323928, 2020). "Tumors from ZMYND8-overexpressing cells exhibited increased Ki-67 positivity and reduced TUNEL positivity compared with controls, reflecting enhanced proliferative activity and reduced apoptosis within the in vivo tumor microenvironment." (PMID 41297414, 2025). "In conclusion, ZMYND8 acted as an epigenetic regulator of NRF2 to enhance the expression of antioxidant genes and reduced iron levels in BCSCs, which protected BCSCs against ferroptosis leading to tumor initiation." (PMID 38488001, 2024). "Previous studies revealed that ZMYND8 and ZMYND11 might act as either transcriptional activators or repressors, and both proteins harbor tumor suppressor functions, particularly in breast, prostate, colon, and ovarian carcinoma." (PMID 36674511, 2023). "Overexpression of ZMYND8 was shown to re-sensitize cells to chemotherapy via the recruitment of the EZH2 methyltransferase and lysine demethylase KDM5C corepressors to the promoters of tumor oncogenes." (PMID 34298819, 2021). "Thus, ZMYND8 can be induced in hypoxic conditions, and it can promote tumor angiogenesis, probably through HIF and VEGF activation, and enhance tumor growth." (PMID 33670804, 2021).
cancer (26 papers, 2014 to 2025). A tumor composed of atypical neoplastic, often pleomorphic cells that invade other tissues. "Although ZMYND8 has been implicated in transcriptional coactivation and epigenetic modulation across various cancers, the mechanisms governing its protein stability, particularly in metastatic contexts, have remained poorly understood." (PMID 41297414, 2025). "Mutations or dysregulation of ZMYND8 expression are associated with cancer development and progression." (PMID 40223119, 2025). "Mutations and altered expression of ZMYND8 are associated with the development and progression of cancer." (PMID 33670804, 2021). "ZMYND8 promotes genes associated with terminal differentiation in opposition to the maintenance of cancer stem cells." (PMID 34298819, 2021). "Loss of ZMYND8 resulted in increased eRNA expression and hyper-enhancer activity that promoted cancer phenotypes." (PMID 27631103, 2016). "Notably, we observed that ZMYND8 antagonizes Polycomb-dependent function to inhibit H3K27me3 level only in hypoxia- or VHL-deficient cancer cells, conditions of which are commonly associated with the up-regulation of HIF transcription factors." (PMID 33593912, 2021). "Formation of the fusion gene may lead to the low activity of PKCB1, and may contribute to cancer, or deregulation of the transcript regulatory network managed by ZMYND8 might cause cancer." (PMID 24533689, 2014). "Thus, this essential role of ZMYND8 in regulating the gene activator function of EZH2 might represent a viable target for the effective treatment of cancers under hypoxia or with VHL deficiency, such as ccRCC." (PMID 33593912, 2021). "ZMYND8 is a transcription factor, a histone H3-interacting protein, and a putative chromatin reader/effector, important for regulating transcription in normal cells, and its mutation, altered expression, and fusion with other genes, are associated with development and progression of cancer." (PMID 33670804, 2021). "Many cancer-related genes, such as ZMYND8, ASAH1, and SELENBP1, were found mis-spliced following the degradation of RBM39." (PMID 40223119, 2025). "Analysis of the Cancer Cell Line Encyclopedia database revealed that, across 30 types of cancers, the ZMYND8 expression level was almost the lowest in MM cell lines." (PMID 40347515, 2025). "The hub genes ATP6AP2, ACTR1A, SYNM, ZMYND8, CAMTA1, SLC39A3, and DHCR24, are associated with cancer development and progression." (PMID 39757707, 2025). "ZMYND8 is a well-known chromatin reader which recognizes acetylated or methylated histones, and involved in transcription regulation, DNA damage and cancer." (PMID 40223119, 2025). "ZMYND8 is also involved in transcription regulation during normal cellular growth, which when disrupted increases cellular processes that lead to cancer start and development." (PMID 37516822, 2023). "Although all of these results indicate that ZMYND8 is important in cancer, they are contradictory, and the actual role of ZMYND8 in cancer is still unclear." (PMID 33670804, 2021). "The function of ZMYND8 in cancer cells is mainly through modulation of histone methylation and acetylation." (PMID 33670804, 2021). "All of these results suggest that, in cancer cells, ZMYND8 positively regulates the expression of differentiation-promoting genes and induces differentiation." (PMID 33670804, 2021). "Many epigenetic effectors, including ZMYND8, contain structurally conserved domains of PHD fingers, and alterations in the PHD finger-containing proteins are linked to cancer." (PMID 33670804, 2021). "In summary, our findings uncover a previously unidentified role of ZMYND8 in regulating PRC2 activities and promoting a Polycomb-dependent to -independent switch of EZH2 functions in hypoxia-exposed or VHL-deficient cancer cells." (PMID 33593912, 2021).
cancer (continued). "ZMYND8 gene is localized at chromosomal region 20q13, which also contains candidate breast cancer oncogenes: MYBL2 (MYB proto-oncogene like 2), ZNF217 (zinc finger protein 217), and AURKA (aurora kinase A)." (PMID 28055972, 2017). "The BRD protein ZMYND8 is a component of the NuRD complex that, along with CHD4, displays mutations or altered expression in various cancers." (PMID 27631103, 2016). "Perturbation of ZMYND8 promotes initiation and progression of cancers." (PMID 36520265, 2022). "Hopefully, in the future, regulation of the expression of ZMYND8 and/or its binding partners may become useful in treating cancer." (PMID 33670804, 2021). "ZMYND8 is essential for regulating transcription during normal cellular growth and DNA repair, the perturbation of which may promote cancer initiation and progression." (PMID 33670804, 2021). "Different cell types, fusion with other genes, and the interaction of ZMYND8 with various binding partners may affect the functions of ZMYND8 in cancers." (PMID 33670804, 2021). "In addition, the activation of ZMYND8 expression through the all-trans-retinoic acid (ATRA) has been shown to inhibit cancer cell proliferation." (PMID 34298819, 2021). "In the future, regulation of expression/activity of ZMYND8 and/or its binding partners may become useful in treating cancer." (PMID 33670804, 2021). "Therefore, more studies are necessary, and they need to be focused not only on ZMYND8, but also on its specific binding partners in different cancer types." (PMID 33670804, 2021). "All of these findings indicate that ZMYND8 may be involved in development and progression of cancer." (PMID 33670804, 2021). "However, the role of ZMYND8 in cancer is still controversial." (PMID 40223119, 2025). "ZMYND8 may induce angiogenesis in cancer, especially in hypoxic conditions." (PMID 33670804, 2021). "However, the reports regarding the influence of ZMYND8 on cancers are ambiguous." (PMID 33670804, 2021). "Mechanistically, ZMYND8 can also anchor activated PKC-binding proteins for phosphorylation or dephosphorylation, hereby controlling the occurrence of malignant tumors." (PMID 36438198, 2022). "We further show that ZMYND8 functions as a scaffold protein that is critical for mediating the EZH2 recruitment of FOXM1 and the expression of cancer migration and invasion genes transactivated by the EZH2-FOXM1 complex." (PMID 33593912, 2021). "Thus, ZMYND8 may prove to be an attractive therapeutic target in a subset of cancer patients." (PMID 34298819, 2021). "This feedback mechanism might be expanded to 28 other types of human cancers because of a significant correlation between ZMYND8 and NFE2L2 mRNAs in these cancers." (PMID 38488001, 2024). "As such, the MST1/2 kinases are better recruited into and inactivated by the STRIPAK complex, which relieves the inhibitory effect of MST1/2 on ZMYND8 recruitment to DSBs, thereby allowing for efficient DSB repair and endowing cancer cells with resistance to radio- and chemotherapy." (PMID 35290241, 2022). "It has been reported that ZMYND8 possesses conserved chromatin-binding modules and can anchor-activated protein-kinase-C- (PKC-) binding proteins to phosphorylation or dephosphorylation, thereby controlling the occurrence of malignant tumors." (PMID 36438198, 2022). "To this end, we analyzed the RNA-seq data in ZMYND8 WT and KO MDA-MB-231 cancer cells." (PMID 33593912, 2021). "As a result, ZMYND8 overexpression impairs EZH2 Polycomb-dependent gene repressor function but activates EZH2 Polycomb-independent gene activator function, thereby enhancing cancer migration and invasion." (PMID 33593912, 2021). "As ZMYND8 interacts with various transcriptional corepressors, chromatin remodeling complexes, histone demethylase/deacetylase, and acetyl transferase enzymes, the role of ZMYND8 in cancers may be related to not just its direct action, but to multiple factors." (PMID 33670804, 2021).
cancer (continued). "However, a direct mechanism of ZMYND8-mediated regulation of cancer stemness was not proposed." (PMID 36674511, 2023).
neurological disorders (1 paper, 2022). "The role of ZMYND8 or mutated ZMYND8 is not known in neurological disorders." (PMID 36064715, 2022).
ZMYND8 also shares sentences with these, for which no sentence is quoted: acute erythroid leukemia (2 papers); acute kidney injury (1); acute megakaryoblastic leukemia (1); Anxiety (1); autism (1); Cranial meningocele (1); Huntington disease (1); Intellectual disability (1); invasive breast carcinoma (1); luminal B breast carcinoma (1); lymphoma (1); metastasis (1); monoclonal gammopathy of undetermined significance (1); Multiple Myeloma (1); Obesity (1); Parkinson disease (1); partial epilepsy (1); plasma cell leukemia (1); polycystic ovary- (1); prion disease (1); Sepsis (1); trigonocephaly (1).